SYCN (syncollin)
Description:
Functions in exocytosis in pancreatic acinar cells regulating the fusion of zymogen granules with each other. May have a pore-forming activity on membranes and regulate exocytosis in other exocrine tissues (By similarity).
Synonyms: INSSA1; SYL; FLJ27441
Tractability: Antibody: UniProt places it where antibodies can reach, with medium confidence; UniProt predicts a signal peptide or a membrane-spanning region.
Gene: Protein-coding gene on chromosome 19 (39,202,825 to 39,204,263, reverse strand). Ensembl gene ENSG00000179751.
Subcellular location: Zymogen granule membrane; Zymogen granule lumen
Pathways (Reactome):
Developmental Biology: Developmental Lineage of Pancreatic Acinar Cells
Gene Ontology:
Molecular function: protein binding
Biological process: exocytosis
Cellular component: zymogen granule membrane; secretory granule membrane
Genetic constraint (gnomAD): Loss-of-function variants: 16 observed, 12.73 expected, observed/expected ratio (o/e) 1.26, 90% interval 0.85 to 1.81. The upper end of that interval is the gene's LOEUF score, 1.81, which puts it in group 6 of 6, group 1 being the genes least tolerant of losing a copy. Missense variants: 226 observed, 189.36 expected, observed/expected ratio (o/e) 1.19, 90% interval 1.07 to 1.33. Synonymous variants: 97 observed, 90.64 expected, observed/expected ratio (o/e) 1.07, 90% interval 0.91 to 1.27.
Homologues: Orthologues: chimpanzee SYCN (99% identical), macaque SYCN (95% identical), dog SYCN (79% identical), pig SYCN (78% identical), mouse Sycn (73% identical), rat Sycn (72% identical), tropical clawed frog SYCN (46% identical), zebrafish sycn.2 (34% identical), zebrafish sycn.1 (34% identical), zebrafish sycn.3 (34% identical).
Diseases named in the same sentence as SYCN in open-access papers:
SYCN is named in the same sentence as 5 diseases in open-access papers, as found by Europe PMC text mining. Sharing a sentence is not in itself a finding about the gene and the disease. The quoted sentences say what the papers report.
pancreatic cancer (4 papers, 2012 to 2020). "Additional serum biomarkers, particularly SYCN and REG1B, when combined with CA19.9, show promise as improved diagnostic indicators of pancreatic cancer, which therefore warrants further validation." (PMID 24007603, 2013). "Syncollin (SYCN) has only very recently been shown to be elevated in the serum of pancreatic cancer patients." (PMID 22515324, 2012). "In the current study, four pancreatic cancer biomarker candidates (SYCN, REG1B, AGR2 and LOXL2) delineated through our previous integrated proteomics analysis of cell line conditioned media and pancreatic juice, were validated in two sample sets of serum/plasma containing a total of 432 samples." (PMID 24007603, 2013). "SYCN has been shown to be increased in the serum of pancreatic cancer patients." (PMID 22515324, 2012).
colon cancer (1 paper, 2013). "SYCN has not previously been studied in other cancers; however REG family gene expression, although not REG1B specifically, has been shown previously to be elevated in colon cancer and inflammatory bowel disease." (PMID 24007603, 2013).
cancer (1 paper, 2013). A tumor composed of atypical neoplastic, often pleomorphic cells that invade other tissues. "SYCN, REG1B and AGR2 were also significantly elevated in PDAC compared to benign controls (p ≤ 0.01), and AGR2 was significantly elevated in PDAC compared to other cancers (p < 0.01)." (PMID 24007603, 2013).
infection (1 paper, 2014). The state of being infected such as from the introduction of a foreign agent such as serum, vaccine, antigenic substance or organism. "In addition, vp1667, vp1665, vp1697, and vp1666, which are homologs to YopN, SycN, YscB, and TyeA respectively, showed upregulation during infection." (PMID 24478989, 2014). "Additionally, upregulation of the YopN (vp1667), SycN (vp1665), YscB (vp1697), and TyeA (vp1666) homologs during HeLa infection implies the functional presence of this complex in the regulation of T3SS1 secretion." (PMID 24478989, 2014).
SYCN also shares sentences with these, for which no sentence is quoted: inflammatory bowel disease (1 paper).